MSLN (mesothelin)
Diseases named in the same sentence as MSLN in open-access papers (continued):
Sharing a sentence is not in itself a finding about the gene and the disease.
infection (7 papers, 2021 to 2025). The state of being infected such as from the introduction of a foreign agent such as serum, vaccine, antigenic substance or organism. "The expression of anti-MSLN scFv in lentiviral vector-transfected T cells was detected using flow cytometry 4 days post-infection to verify the CAR transfection efficiency." (PMID 37359558, 2023). "A more detailed analysis, evaluating the relative percentages of living cells after infection, showed that residual viability ranged from 80 to 45% into the cell lines with remarkable MSLN expression." (PMID 33418877, 2021). "HEK293 cells, physiologically negative for MSLN, were proven not to express endogenous MSLN (data not shown); thus, they were stably transduced with exogenous MSLN to allow infection by THV_SS1." (PMID 33418877, 2021). "Analysis of the four migratory DC subsets following infection revealed that the number of migratory CD11b+CD103− cDC2 and DN cells was significantly decreased in the msLN of Hp-infected Chi3l1−/− mice relative to WT mice." (PMID 41012147, 2025). "The infection efficiency was evaluated using flow cytometry using anti-HER2, anti-EpCAM, and anti-MSLN antibodies." (PMID 38702509, 2024). "Wild-type and MSLN+ HEK293 cells were infected with different dosage of THV_SS1 (MOI 0.001, 0.01, 0.1, 1 for HEK293-MSLN; MOI 1 for HEK293), and viral spread was monitored until reaching the infection of the whole cell monolayer." (PMID 33418877, 2021). "Importantly, the infection was unaffected by the presence of soluble mesothelin, SMRP, at a concentration range similar to that exhibited by patients affected by mesothelin-expressing tumors." (PMID 33418877, 2021). "As for CAR-T cells, only the highest concentrations of SMRP slightly affected THV infection; thus, both THV_SS and THV_SS1 retained their ability to efficiently infect MSLN+ cells in the presence of the soluble mesothelin (SMRP) at the concentrations observed in cancer patients." (PMID 33418877, 2021). "As HEK293 STING KO cells do not express MSLN, its transduction was preparatory to render these cells proficient for THV-SS1 infection." (PMID 33418877, 2021).
colorectal (2 papers, 2023 to 2026). "Significantly, elevated MSLN expression was restricted to liver-metastatic cells, absent in brain or lung metastases." (PMID 41513618, 2026).
hematologic neoplasms (2 papers, 2021 to 2025). "For China, in addition to common targets for hematological tumors, there has been an increase in trials for some less common targets in solid tumors, such as CLDN18.2, HER2, and MSLN in recent years." (PMID 41142719, 2025).
epithelial neoplasm (1 paper, 2018). A benign or malignant neoplasm that arises from and is composed of epithelial cells. "MSLN is one of tumor antigen expressed on the various epithelial neoplasms." (PMID 30558663, 2018).
MSLN also shares sentences with these, for which no sentence is quoted: neuroblastoma (9 papers); carcinosarcoma (4); head and neck cancer (4); lung squamous cell carcinoma (4); metastatic cancer (4); thymoma (4); B cell lymphoma (3); Lewis lung carcinoma (3); ovarian adenocarcinoma (3); prostate adenocarcinoma (3); serous ovarian tumors (3); stomach cancer (3); thyroid cancer (3); benign neoplasm (2); clear cell carcinoma (2); esophageal adenocarcinoma (2); gastrointestinal tumors (2); Gynecological Tumors (2); hematological tumors (2); mucinous carcinomas of the ovary (2); respiratory failure (2); sarcoma (2); adrenal tumors (1); autoimmune pancreatitis (1); benign ovarian tumours (1); biliary tract cancer (1); bladder transitional cell carcinoma (1); bowel cancer (1); bronchitis (1); cardiac arrest (1).
A further 46 diseases each share a sentence with MSLN in 1 paper.